TAS2R31 (taste 2 receptor member 31)
Description:
Receptor that may play a role in the perception of bitterness and is gustducin-linked. May play a role in sensing the chemical composition of the gastrointestinal content. The activity of this receptor may stimulate alpha gustducin, mediate PLC-beta-2 activation and lead to the gating of TRPM5 (By similarity). Activated by the sulfonyl amide sweeteners saccharin and acesulfame K.
Synonyms: T2R31; T2R44; T2R53; TAS2R44
Tractability: Small molecule: a high-quality ligand is known. Antibody: its Gene Ontology location is reachable by antibodies, with high confidence; UniProt predicts a signal peptide or a membrane-spanning region. PROTAC: a small molecule that binds it is known.
Target class: Membrane receptor; Taste receptor (taste family GPCR); Taste family G protein-coupled receptor
Gene: Protein-coding gene on chromosome 12 (11,030,387 to 11,031,407, reverse strand). Ensembl gene ENSG00000256436.
Subcellular location: Membrane
Pathways (Reactome):
Signal Transduction: Class C/3 (Metabotropic glutamate/pheromone receptors); G alpha (i) signalling events
Sensory Perception: Sensory perception of sweet, bitter, and umami (glutamate) taste
Gene Ontology:
Molecular function: bitter taste receptor activity; G protein-coupled receptor activity
Biological process: detection of chemical stimulus involved in sensory perception of bitter taste; G protein-coupled receptor signaling pathway; sensory perception of taste
Cellular component: membrane; plasma membrane
Genetic constraint (gnomAD): Loss-of-function variants: 0 observed, 0.34 expected, observed/expected ratio (o/e) 0, 90% interval 0 to 1.86. That is too few expected variants to judge how well the gene tolerates losing a copy. Missense variants: 352 observed, 320.18 expected, observed/expected ratio (o/e) 1.1, 90% interval 1.01 to 1.2. Synonymous variants: 118 observed, 118.02 expected, observed/expected ratio (o/e) 1, 90% interval 0.86 to 1.16.
Homologues: Orthologues: dog CAFA-T2R43 (60% identical), mouse Tas2r120 (49% identical), rat Tas2r120 (48% identical), rat Tas2r136 (47% identical), mouse Tas2r136 (46% identical). Paralogues in human: TAS2R43 (89% identical), TAS2R46 (85% identical), TAS2R30 (80% identical), TAS2R50 (67% identical), TAS2R20 (66% identical), TAS2R19 (65% identical), TAS2R14 (45% identical), TAS2R13 (43% identical), TAS2R7 (38% identical), TAS2R9 (38% identical), TAS2R10 (36% identical), TAS2R42 (34% identical), and 11 more.
Diseases named in the same sentence as TAS2R31 in open-access papers:
TAS2R31 is named in the same sentence as 6 diseases in open-access papers, as found by Europe PMC text mining. Sharing a sentence is not in itself a finding about the gene and the disease. The quoted sentences say what the papers report.
colon cancer (1 paper, 2024). "Utilizing univariate Cox regression analysis, we identified seven TAS2Rs genes associated with prognosis in colon cancer patients, including TAS2R4, TAS2R5, TAS2R14, TAS2R19, TAS2R20, TAS2R31, and TAS2R38." (PMID 38999959, 2024). "Our results show that compared to normal colon tissue, the expression levels of multiple bitter taste receptor genes are elevated in colon cancer tissue, including TAS2R4, TAS2R5, TAS2R14, TAS2R19, TAS2R20, TAS2R31, and TAS2R38." (PMID 38999959, 2024).
TAS2R31 also shares sentences with these, for which no sentence is quoted: breast carcinoma (1 paper); cancer (1); glioma (1); infection (1); melanoma (1).